FGFR2 (fibroblast growth factor receptor 2)
Diseases named in the same sentence as FGFR2 in open-access papers (continued):
Sharing a sentence is not in itself a finding about the gene and the disease.
gastric cancer (continued). "Tumor microenvironment adaptations also present a challenge to target FGFR2, as diffuse-type gastric cancer cells can switch their driver pathways from FGFR2b expression to CXCR4 under hypoxia via SDF1 produced by cancer associated fibroblasts." (PMID 41303727, 2025). "The identification of mutations in BRCA2, PIK3CA, and fibroblast growth factor receptor 2 (FGFR2) genes particularly underscored their potential as predictive biomarkers and therapeutic targets in gastric cancer." (PMID 40869030, 2025). "Several mechanisms have been studied using patient-derived models of FGFR2-amplified gastric cancer." (PMID 41303727, 2025). "FGFR2 alterations are relatively uncommon in gastric cancer, but have important clinical implications given the promising efficacy of FGFR2-targeting therapeutics such as bemarituzumab." (PMID 40676191, 2025). "DDX6 overexpression was observed in 60% of gastric cancer samples and 83% of FGFR2-positive cases, and DDX6 knockdown reduced FGFR2 and HER2 protein expression without affecting mRNA levels." (PMID 41303727, 2025). "Co-expression of FGFR2 and other relevant biomarkers in gastric cancer, such as HER2, EGFR, MET, and Claudin 18.2, has also been a topic of interest." (PMID 41303727, 2025). "WDR11, a gene responsible for encoding a protein in the WD repeat-containing protein family, has been identified as a rare fusion partner with FGFR2 in gastric cancer." (PMID 41357601, 2025). "MAPK dependent phosphorylation of DNA PKcs has been observed in FGFR2 amplified gastric cancer lines, leading to faster ligation of DNA ends and reduced apoptosis after irradiation." (PMID 41150770, 2025). "FGFR2 has emerged as both a promising biomarker with prognostic significance and a potential therapeutic target in gastric cancer." (PMID 41303727, 2025). "The prevalence and prognostic significance of FGFR2 amplification were described in 2015 in a cohort of 61 patients with advanced-stage gastric cancer undergoing treatment with chemotherapy." (PMID 41303727, 2025). "Despite being less frequently observed than gene amplification, several FGFR2 fusion genes have been identified in gastric cancer as well as in common bile duct cancer, hepatocellular carcinoma, pancreatic cancer, and sarcomas." (PMID 41303727, 2025). "The identification of new biomarkers such as fibroblast growth factor receptor 2 (FGFR2) has opened new pathways for directed therapy in gastric cancer." (PMID 41303727, 2025). "In a gastric cancer model containing FGFR2 amplified on ecDNA, BBI-2779 suppresses tumour growth and prevents ecDNA-mediated acquired resistance to the pan-FGFR inhibitor infigratinib, resulting in potent and sustained tumour regression in mice." (PMID 39506153, 2024). "FGFR2 promotes gastric cancer progression by inhibiting the expression of Thrombospondin4 via PI3K-Akt-Mtor pathway." (PMID 38575325, 2024). "The synergistic antitumour activity and pharmacodynamics of BBI-2779 was evaluated in combination with the pan-FGFR tyrosine kinase inhibitor infigratinib in the FGFR2-amplified ecDNA+ gastric cancer SNU16 xenograft tumour model." (PMID 39506153, 2024). "In gastric cancer, increased expression of FGFR2 has been correlated with tumor depth and clinical stage." (PMID 38491511, 2024). "Given their roles as oncogenic drivers, MET and FGFR2 overexpression are considered significant therapeutic targets in gastric cancer, along with Her2neu overexpression." (PMID 38496894, 2024). "CAFs derived‐FGF7 is a mesenchyme‐specific heparin‐binding growth factor, which can bind to FGFR2 and promote cell migration and invasion in gastric cancer by upregulating THBS1 and elevating the activity of the PI3K/Akt/mTOR signaling pathway." (PMID 38778448, 2024). "For instance, for gastric cancer, tumor heterogeneity is a challenge, affecting the accuracy of FGFR2 amplification or overexpression and clinical applications for therapeutic targeting." (PMID 38255923, 2024).
gastric cancer (continued). "Other researchers reported the overexpression of FGFR2 as an intrinsic resistance to MET inhibitors with patient-derived gastric cancer xenograft models." (PMID 38892160, 2024). "Upregulation of FGFR2 has been observed in several cancers, including breast, gastric cancer and NPC." (PMID 38637504, 2024). "FGFR2 signalling was found to promote human gastric cancer progression through the downregulation of TSP4 via the PI3K-AKT-mTOR pathway." (PMID 38473753, 2024). "The exploration of FGFR2’s role in gastric cancer has unveiled its critical contribution to the disease’s pathogenesis and progression, particularly through its involvement in cell proliferation, survival, angiogenesis, and resistance to chemotherapy." (PMID 39195304, 2024). "As oncogenic drivers, MET and FGFR2 overexpression, in addition to Her2neu overexpression, are recognized as potential therapeutic targets in gastric cancer." (PMID 38496894, 2024). "The creation of small molecule inhibitors and monoclonal antibodies targeting FGFR2 has shown promise in clinical trials, emphasizing the potential of FGFR2 in targeted therapies for gastric cancer." (PMID 39195304, 2024). "Initial research into inhibitors that block FGFR2 or its related pathways has shown promising results, offering a potential avenue to improve outcomes for patients with FGFR2-related gastric cancer." (PMID 39195304, 2024). "The therapeutic landscape for gastric cancer includes small molecule inhibitors that act on FGFR2’s tyrosine kinase domain." (PMID 39195304, 2024). "Aflofanib (RPT835) is a novel selective allosteric FGFR2 inhibitor, which has been evaluated in breast, ovarian, and gastric cancers." (PMID 38255923, 2024). "Liquid biopsy, involving the analysis of circulating tumor DNA (ctDNA) and other biomarkers from blood samples, offers a non-invasive method to monitor FGFR2 alterations and treatment response in gastric cancer." (PMID 39195304, 2024). "Combination of FGFR inhibitors with EGFR or MAPK pathway inhibitors can also be considered given that FGFR inhibitor AZD4547 has synergic activity with EGFR inhibitor cetuximab in gastric cancer cells with FGFR2 amplifications." (PMID 38255923, 2024). "The literature included in this review encompasses peer-reviewed research articles, clinical trials, and reviews that specifically investigate FGFR2 in gastric cancer." (PMID 39195304, 2024). "The importance of FGFR2 in gastric cancer is underscored by its genetic alterations, role in oncogenic signaling pathways, and potential as a therapeutic target." (PMID 39195304, 2024). "Grygielewicz and colleagues observed these morphological changes in the gastric cancer cell line SNU-16 (FGFR2 amplification), following chronic exposure to medications like infigratinib." (PMID 38255923, 2024). "FGFR-2 was found to be amplified in 10% of gastric cancers and seems to correlate with a poorer prognosis." (PMID 39682222, 2024). "While many correlative studies and new treatment avenues have highlighted FGFR2 as a potential target for gastric cancer, preclinical models have highlighted FGFR2b as a particularly attractive target due to its pro-tumorigenic functions and specificity." (PMID 39195304, 2024). "The analysis of circulating tumor DNA (ctDNA) shows that gastric cancer patients with FGFR2 amplification have significantly shorter OS than those without FGFR2 amplification." (PMID 38831455, 2024). "Among these, dovitinib and AZD4547 stand out in their efficacy in FGFR2-amplified gastric cancer models." (PMID 39195304, 2024). "Significant efforts have gone into identifying targetable alterations in gastric cancer, ultimately yielding the Fibroblast Growth Factor Receptors (FGFRs) family, specifically FGFR2 as a promising target." (PMID 39195304, 2024).
gastric cancer (continued). "In this review, we outline the underlying biology of FGFR2, its putative role in GC, and the various FGFR2-targeted agents currently in clinical trials for gastric cancer patients as well as postulate some challenges in adopting these therapeutics for clinically meaningful benefit." (PMID 39195304, 2024). "The researchers observed that ctDNA sequencing identifies FGFR2 amplification missed by tissue testing in patients with advanced gastric cancer." (PMID 37509254, 2023). "FGFR2 promotes gastric cancer progression by downregulating thrombospondin‐4 (TSP4) through the PI3K/AKT/mTOR signaling axis." (PMID 37750089, 2023). "Collectively, these data show that the expression (combination of intensity of immunostaining and amount of immunopositive tumor areas) of FGFR2 is heterogeneous in gastric cancer." (PMID 38155920, 2023). "The results of other large studies also demonstrate a high prevalence of FGFR2 heterogeneity in patients with gastric cancer." (PMID 38155920, 2023). "In a nationwide plasma genomic profiling study GOZILA in Japan, FGFR2 amplification status in paired tissue and plasma samples with advanced gastric cancer was assessed." (PMID 38155920, 2023). "We aimed in the current study to find the frequency of MET and FGFR2 amplification and their impact on gastric cancer treatment based on real-world data." (PMID 38137393, 2023). "Fibroblast growth factor receptor 2 (FGFR2) alterations are found in between 9–61% of patients with gastric cancer depending on the stage and methods used." (PMID 37370858, 2023). "These incidence findings were consistent with previous studies, with MET amplification reported in 4–10% of cases and FGFR2 amplification in 4–15% of gastric cancer cases." (PMID 38137393, 2023). "Among gastric cancer patients, 39 (6.4%) patients had FGFR2 amplification, and 22 (3.6%) patients had MET amplification." (PMID 38137393, 2023). "We have encountered a rare subset of gastric cancer patients with both FGFR2 and MET amplification on the same tumor specimen." (PMID 38137393, 2023). "Fibroblast growth factor receptor 2 (FGFR2) plays an important role in the pathogenesis of various malignant tumors, including gastric cancer." (PMID 38155920, 2023). "The CpG site of the FGFR2 gene was hypomethylated in the metastatic group, and the overexpression of the FGFR2 protein in gastric cancer indicates a poor prognosis." (PMID 37260411, 2023). "EGFR and HER2 are the most recognized tyrosine kinase receptors in gastric cancer, while overexpression of other recognized tyrosine kinase receptors in gastric cancers includes fibroblast growth factor receptor 2 (FGFR2) and MET." (PMID 38186572, 2023). "A remarkable example of intratumor heterogeneity is the assessment of FGFR2 expression in our patients with stage III gastric cancer." (PMID 38155920, 2023). "Taken together, the results of many studies demonstrate the need to correctly select patients with gastric cancer for FGFR2-targeted therapy." (PMID 38155920, 2023). "Numerous studies consistently link MET and FGFR2 amplification with advanced tumor stages, metastasis, and poorer survival outcomes in gastric cancer." (PMID 38137393, 2023). "Several FGFR inhibitors have been investigated as monotherapy or combined with chemotherapy in patients with FGFR2-overexpressed or FGFR2-amplified gastric cancers with mixed results." (PMID 37370858, 2023). "FGFR2 amplification was more frequently detected by ctDNA sequencing in 28 (7.7%) of 365 patients with advanced gastric cancer than by tissue analysis alone (2.6–4.4%)." (PMID 37509254, 2023). "In translational clinical studies, gastric cancers with high-level clonal FGFR2 amplification have also been shown to respond better to treatment with selective FGFR tyrosine kinase inhibitors, whereas cancers with low-level amplification did not respond." (PMID 38155920, 2023).
gastric cancer (continued). "Our study findings are in line with previous research, reaffirming the prognostic significance of MET and FGFR2 amplification in gastric cancer." (PMID 38137393, 2023). "Although most patients had mutually exclusive FGFR2 or MET amplifications, two (0.3%) gastric cancer patients had both FGFR2 and MET amplifications detected in the same tumor specimen using NGS." (PMID 38137393, 2023). "The FIGHT trial also showed that around 30% patients with HER2-negative advanced gastric cancer had FGFR2b overexpression or FGFR2 amplification, which supports the development of FGFR2 as a therapeutic target." (PMID 37238666, 2023). "As with gastric carcinoma, FGFR2-amplified esophageal adenocarcinomas showed different morphological growth patterns, like tubular, mucinous, and poorly cohesive carcinomas." (PMID 36416959, 2023). "FGFR2 amplification had a prognostically unfavorable effect (p = 0.005) in the group of primary operated gastric carcinomas." (PMID 36416959, 2023). "The percentage of FGFR2-amplified esophageal adenocarcinoma in our cohort (4.1%) is consistent with the rate reported in the literature for gastric carcinomas." (PMID 36416959, 2023). "From 119 cases with primary gastric carcinoma and corresponding lymph node metastasis, 15 tumor pairs showed FGFR2 amplification." (PMID 36416959, 2023). "The authors confirmed high heterogeneity of FGFR2 expression in gastric carcinomas, a finding that fits excellently with our results." (PMID 36416959, 2023). "Specifically, 93% of gastric carcinoma and 83% of esophageal adenocarcinoma exhibited intratumoral heterogeneity of FGFR2 amplification." (PMID 36416959, 2023). "Due to the significant amplification of the FGFR2 gene in gastric cancer, it has become the most popular factor of the FGFR family in GC research." (PMID 36147913, 2022). "In gastric cancer, an imbalance of the ratio of FGFR2-IIIb to FGFR2-IIIc of the gene encoding the fibroblast growth factor receptor 2 has been recently reported." (PMID 35158828, 2022). "The significance of fibroblast growth factor receptor 2 (FGFR2) in gastric cancer (GC) has been studied predominantly in Asian patient cohorts." (PMID 35167603, 2022). "There were several studies revealed that the FGFR2 markedly overexpressed in gastric cancer tissues." (PMID 35498538, 2022). "Here, our study first reported the relationship between FGFR2 overexpression and early-onset gastric cancer." (PMID 35498538, 2022). "On the other hand, cross-talk between ERBB and FGFR receptors has also been described, with ERBB3 required for the maintenance of FGFR2 phosphorylation and proliferation in some FGFR2-amplified gastric cancer cells." (PMID 35501832, 2022). "Amplification of FGFR2 was found in up to 10% of gastric cancers and FGFR2 gene fusions in up to 20% of intrahepatic cholangiocarcinomas and up to 6% of urothelial carcinomas." (PMID 36231142, 2022). "It is now confirmed that only high CNVs actually translate into high protein expression, which decreases the prevalence of FGFR-positive patients, usually to a low percentage of the overall population (e.g., 4% for FGFR2-amplified gastric cancer)." (PMID 36231142, 2022). "Seeding was frequent in gastric carcinoma patients with FGFR2 amplification, in patients with high TMB, or in those who were female." (PMID 36292044, 2022). "Since FGFR2 has two isoforms, IIIb type and IIIc type, it is important to examine the frequency of FGFR2-IIIc expression among FGFR2 overexpressing gastric cancers." (PMID 33633310, 2021). "FGFR2 expression was elevated in gastric cancer tissues, and treatment of gastric cancer cells with FGF7 stimulated cell migration and invasion through thrombospondin upregulation." (PMID 33801580, 2021).
gastric cancer (continued). "FGFR2 expression has also been indicated as a potential predictor of treatment response in advanced gastric cancer patients who have been treated with Pazopanib in combination with Capecitabine and Oxaliplatin." (PMID 34765202, 2021). "Although novel to brain tumors, FGFR2 amplification has been reported in gastric cancer where it imparts poor prognosis, triple-negative breast cancer, hormone-resistant prostate cancer and in an isolated case of colorectal carcinoma." (PMID 33853673, 2021). "We also have reported that an FGFR2 phosphorylation inhibitor is useful for the treatment of gastric cancer with FGFR2 amplification." (PMID 33633310, 2021). "Among nine patients with FGFR2-amplified gastric cancer, three demonstrated a long-term response to AZD4547." (PMID 34639155, 2021). "A large multicenter study found FGFR2 amplification in 7.4, 4.6 and 4.2% of gastric cancers from patients in the United Kingdom, China and Korea (n = 961)." (PMID 34068954, 2021). "High‐level FGFR2 amplification is associated with the lower response, resistance to chemotherapy, shorter PFS and shorter OS in gastric cancers." (PMID 33655556, 2021). "A total of 33 gastric cancer including 28 FGFR2-positive tumors and five FGFR2-negative tumors were examined FGFR2 amplification by FISH." (PMID 33633310, 2021). "Gastric cancers with FGFR2 amplification, which was observed in 3–10% of all gastric cancers, has been found to be associated with malignant progression." (PMID 33633310, 2021). "Animal experiments show retarded tumour growth in FGFR2‐amplified gastric cancer treated with FGFR inhibitors." (PMID 33655556, 2021). "Although a reliable biomarker is desired to identify the gastric cancer patients who are candidates for FGFR2 targeting therapy, however suitable FGFR2 antibodies that are specific for the FGFR2IIIb and FGFR2IIIc types are not yet available, so far." (PMID 33633310, 2021). "The empirical target Ctrough of 60 μg/mL for bemarituzumab was to achieve > 95% receptor occupancy based on in vitro data, including receptor occupancy using multiple FGFR2-amplified gastric cancer cell lines." (PMID 32965540, 2020). "Other recognized tyrosine kinase receptors in gastric cancer include fibroblast growth factor receptor 2 (FGFR2) and MET." (PMID 32850413, 2020). "Morphological changes defined by cells becoming more spindle shaped were observed in the gastric cancer cell line SNU-16 (FGFR2 amplification), following chronic exposure to AZD4547, infigratinib or PD173074." (PMID 35582593, 2019). "Co-targetting of FGFR and ILK, an upstream receptor of GSK3β in FGFR2 amplified gastric cancer cell lines, resulted in synergistic anti-tumour responses." (PMID 35582593, 2019). "We observed synergistic effects on KatoIII cells as well as three additional gastric cancer cell lines with FGFR2 amplification when AZD4547 was combined with small molecular inhibitors Cpd22 and lapatinib targeting ILK and EGFR/HER2, respectively." (PMID 31076567, 2019). "In this study, we applied a kinome-wide CRISPR/Cas9 screen to systematically identify kinases that are determinants of sensitivity to a potent FGFR inhibitor AZD4547 in KatoIII cells, a gastric cancer cell line with FGFR2 amplification." (PMID 31076567, 2019). "The secretion of FGF7 (a ligand of fibroblast growth factor receptor 2 [FGFR]2) by gastric fibroblasts is likely to contribute in a paracrine manner to the remarkable cell proliferation seen in scirrhous gastric cancer with FGFR2 overexpression." (PMID 31703077, 2019). "Using a kinome-wide CRISPR/Cas9 screen, 20 kinases involving ILK (Integrin-linked kinase), SRC, and EGFR signaling were found to alter sensitivity to FGFR inhibition in FGFR2 amplified gastric cancer cell lines." (PMID 35582593, 2019).